INS (insulin)
Diseases named in the same sentence as INS in open-access papers (continued):
Sharing a sentence is not in itself a finding about the gene and the disease.
Hyperglycemia (continued). "However, it is reported that a Western diet containing high sugar and high fat exacerbated imiquimod-induced psoriasis-like dermatitis and topical imiquimod treatment induced hyperglycemia via impairment of insulin secretion in mice." (PMID 37762500, 2023). "The pancreatic β-cells produce and synthesize insulin that most importantly regulates blood glucose levels, and its impairment leads to a lack of insulin synthesis and subsequent metabolic control, leading to hyperglycemia." (PMID 37755075, 2023). "Therefore, our goal is to evaluate the effects of chronic hyperglycemia and insulin treatment on IL1β immunoreactivity in myenteric neurons and their different subpopulations along the duodenum–ileum–colon axis." (PMID 36982878, 2023). "At least during exposure to permissive hyperglycemia, the combination of empagliflozin and insulin does not appear to increase the risk of hypoglycemia." (PMID 37194077, 2023). "Therefore, GLP-1 protects against hyperglycaemia by enhancing insulin secretion and inhibiting glucagon secretion." (PMID 37237989, 2023). "GLP-1RA alleviates hyperglycemia by potentiating nutrient-induced insulin secretion." (PMID 36980281, 2023). "In addition to hyperglycemia, diabetic TH mice showed higher serum levels of triglycerides and insulin compared to both control groups." (PMID 38130754, 2023). "T2DM is characterized by chronically elevated blood glucose (hyperglycemia) and elevated blood insulin (hyperinsulinemia) owing to defective insulin secretion by pancreatic β-cells and the inability of insulin-sensitive tissues to respond appropriately to insulin." (PMID 38231849, 2023). "In addition, GDM women have increased hepatic insulin-stimulated glucose production compared with healthy pregnant controls, particularly in late gestation, which contributes to the hyperglycemia in GDM." (PMID 37650554, 2023). "In addition, PI3K monotherapy affects insulin metabolism, leading to side effects such as hyperglycemia, anorexia, and nausea." (PMID 37834269, 2023). "Ingesting sugary snacks could lead to postprandial hyperglycemia followed by hypoglycemia with an excess of insulin action, especially in people with lower glucose effectiveness." (PMID 36837857, 2023). "Besides, slightly more people in CON injected short-acting insulin that evening because of hyperglycaemia, making it further unlikely that late-evening eating played an important role." (PMID 36879098, 2023). "Finally, increased Mondo A/Mlx signaling in beta-cells in persistent hyperglycemia is linked to increase in TXNIP, inflammation, impaired insulin secretion, and apoptosis." (PMID 38292764, 2023). "The Pedersen hypothesis from 1952 states that a fetus will develop hyperinsulinism in response to maternal hyperglycaemia, as maternal glucose can travel freely across the placenta, while maternal insulin cannot." (PMID 37442824, 2023). "Thus, an obesogenic diet resulted in increased body weight, hyperglycemia, reduced insulin levels, and glucose intolerance in Trpm7R/R mice relative to WT controls." (PMID 36574297, 2023). "Furthermore, the oral administration of L. sakei OK67 suppressed fasting blood glucose, hyperglycemia, body weight, body fat, epididymal fat, and insulin levels in HFD-treated mice." (PMID 37447399, 2023). "Due to the low glycemic load, the VLCKD may improve hyperglycemia, insulin sensitivity, dyslipidemia, and blood pressure, resulting in a reduction in inflammatory status." (PMID 37892519, 2023). "The excessive glycogen accumulates in hepatocytes because of the insulin-independent passage of glucose into hepatocytes during the period of hyperglycemia, followed by insulin-mediated conversion into hepatic glycogen; both elevated glucose and insulin are required." (PMID 37047105, 2023). "GSK3β was found to mediate the insulin secretion dysfunction induced by chronic hyperglycemia." (PMID 37008937, 2023).
Hyperglycemia (continued). "Insulin is a drug candidate for treating severe hyperglycemia in people with T2D and COPD." (PMID 37242426, 2023). "Our model shows that exogenous insulin administration initially causes fasting and postprandial hyperglycemia, associated with ROS overproduction without hepatic inflammation." (PMID 37110230, 2023). "Impaired insulin signaling, a well-known abnormality in the metabolic syndrome, leads to lower uptake of glucose in skeletal muscles, and an upregulation of hepatic gluconeogenesis resulting in hyperglycemia." (PMID 36991398, 2023). "The function of APT1 was blocked in chronic hyperglycemia, leading to defective insulin secretion." (PMID 37601108, 2023). "The diabetology staff usually provide a basic training to all the school personnel to ensure the management of hypoglycemia, hyperglycemia, and, in the case of an emergency, one or more school staff members receives in-depth training on insulin and/or technology management at their request." (PMID 37373970, 2023). "Hyperglycemia was more commonly corrected with dietary and physical activity modification among women in the late diagnosis group, and dietary and physical activity modification with insulin therapy in the early diagnosis group." (PMID 37241086, 2023). "Herein, we took advantage of mussel‐inspired chemistry and designed a novel self‐crosslinkable polymer‐based matrix MN (mMN) patch capable of encapsulating highly concentrated insulin, with super swelling capability, and rapid delivery of insulin at hyperglycemia." (PMID 37718654, 2023). "Moreover, oxidative stress induced by hyperglycaemia has been shown to inhibit the expression of the insulin gene and promote beta-cell apoptosis." (PMID 37623239, 2023). "When the fetus inherits a maternal pathogenic GCK variant, normal fetal growth is anticipated, and insulin treatment of maternal hyperglycaemia is not recommended." (PMID 37653058, 2023). "Inflammatory cytokines, such as interleukin-1 (IL-1), interleukin-6 (IL-6), and tumour necrosis factor-α (TNF-α), suppress insulin release and induce insulin resistance, and elevated levels of IL-6 promote hyperglycaemia by releasing glucose from hepatic glycogen reserves." (PMID 38255162, 2023). "However, to counteract hyperglycemia and maintain healthy blood glucose levels, women with T1D tend to increase their insulin doses when they experience reduced insulin sensitivity or high blood glucose during the luteal phase." (PMID 36833469, 2023). "This suggests that insulin resistance in muscle is enough to cause glucose intolerance, but not hyperglycemia." (PMID 37628845, 2023). "Previous reports showed that phenolic compounds acted on ATP-sensitive K+ channels and controlled hyperglycemia, so the phenolic compounds present in the extract may be responsible for insulin-mimetic action." (PMID 36826003, 2023). "In addition, glucose transport, INS secretion, action, and correction of hyperglycemia connected to INS resistance in Polycystic ovary rats are all improved by dietary flaxseed." (PMID 37534085, 2023). "In particular, it was found that hyperglycemia in pancreatic beta cells leads to erroneous translocation of this protein into the plasma membrane of the cell, a significant decrease in the ATP pool, and impaired insulin secretion." (PMID 37507997, 2023). "However, adipocytes undergoing cellular senescence are characterized by altered lipid metabolism and insulin resistance that activate feedback loops, further increasing hyperglycemia, insulin resistance, and cellular senescence." (PMID 38203703, 2023). "Therefore, in the present double-blind, randomized clinical trial, effects of glargine and regular insulin on hyperglycemia were compared with regular insulin alone in diabetics undergoing off-pump CABG." (PMID 37342663, 2023).
Hyperglycemia (continued). "Additionally, hyperglycemia leads to the production of advanced glycosylation end products (AGEs), which together with ROS leads to impairment in insulin gene transcription and pancreatic β-cell death." (PMID 37755075, 2023). "Furthermore, the postoperative spontaneous fluctuations of blood glucose levels were actively modified using insulin therapy protocol to avoid potentially deleterious hyperglycemia." (PMID 37620974, 2023). "In addition, in the cardiac tissue of diabetic rats, PG levels are reduced compared to normal rats or diabetic rats treated with insulin to prevent hyperglycemia, providing a potential link between decreased PG and impaired mitochondrial function in diabetes." (PMID 37242739, 2023). "An important observation is that stress states in seriously ill neonates may lead to hyperglycemia by increasing the level of gluconeogenetic hormones, adrenaline, norepinephrine, and cortisol, with the opposing effects of insulin." (PMID 37371878, 2023). "T2D is characterized by insulin insensitivity in target tissues resulting in hyperglycemia." (PMID 37144869, 2023). "Earlier we supposed, that inflammation in the pancreas caused by diabetic agent streptozotocin first triggers processes aimed at restoring the functional integrity of the pancreatic tissue, and, combined with hyperglycemia, affect the generation of insulin+ cells in exocrine pancreas." (PMID 38019818, 2023). "The rats were fed orally with the extract at a dose of 300 mg/kg, showing a reduction in hyperglycemia (12.5%), pancreatic lipid peroxidation, and an increase in insulin levels in the diabetic group (36%), as well as an increase in the number of active pancreatic β cells." (PMID 37432178, 2023). "Ten weeks after the onset of hyperglycemia, myenteric whole-mount preparations from the duodenum, ileum and colon of streptozotocin-induced diabetic, insulin-treated diabetic and control rats were prepared for TLR4/peripherin double-labelling fluorescent immunohistochemistry." (PMID 36672637, 2023). "DC impairment was rescued by insulin-based normalization of hyperglycaemia." (PMID 38093014, 2023). "Our previous study demonstrated that once the epigenetic imprint was left on the offspring by intrauterine hyperglycemia, even with insulin treatment to maintain normal maternal glucose, it is important for the offspring to keep a healthy diet in case of emergence of dysfunction." (PMID 37255932, 2023). "On the other hand, none of the other factors we examined, including T2D, use of cholesterol-lowering agents, and use of anti-hyperglycemia medications, such as sulfonylureas, insulin, or metformin, were statistically significant in their association with GBD after sleeve gastrectomy." (PMID 37223192, 2023). "Following these changes, exercise releases compensatory insulin and prevents hyperglycemia." (PMID 37151681, 2023). "SC insulin delivery creates a paradoxical peripheral hyperinsulinemia necessary to achieve minimal insulin concentration in the portal system able to inhibit hepatic glucose production, thus, preventing fasting hyperglycemia." (PMID 37229215, 2023). "Hyperglycemia alone, i.e., in an insulin deficient and non-obese context, has been shown to rapidly increase cardiac expression of Pdk4 and Ucp3, and to provoke metabolic inflexibility and cardiac dysfunction in mice." (PMID 37626210, 2023). "Despite insulin doses up to 4 units/kg/day, hyperglycaemia had persisted." (PMID 37562398, 2023). "An antidiabetic class switch was performed in 9 (9%) patients, for example, from repaglinide to DPP-4 inhibitor or sulfonylurea plus DPP-4 inhibitor to metformin in case of hypoglycemia, and from GLP1 receptor agonist to long-acting insulin plus glinide in case of hyperglycemia." (PMID 37760514, 2023). "As muscle and liver cells fail to absorb glucose from the blood, blood glucose levels remain abnormally high and insulin levels may rise in an attempt to correct the hyperglycemia." (PMID 37899888, 2023).
Hyperglycemia (continued). "Under insulin-resistant states, insulin response is impaired in liver, skeletal muscle, white adipose tissue, the vasculature, and the kidney leading to hyperglycemia, hyperinsulinemia, high plasma free fatty acid levels, and inflammation-activated serine/threonine kinases." (PMID 37196634, 2023). "The combined effect of GLP-1 and GIP in stimulating insulin secretion in a glucose-dependent manner, prolonging stomach emptying time, and suppressing hunger, thus, significantly improving the management of postprandial hyperglycaemia in particular." (PMID 37133312, 2023). "Among these miRNAs, miR-542-5p and miR-182 could lead to potential hyperglycemia and modulate the insulin secretion by targeting FOXO1." (PMID 37373469, 2023). "While recognizing the significance and health advantages of enhanced insulin sensitivity, our primary focus was on mitigating postprandial hyperglycemia (defined as a primary outcome) due to its direct correlation with acute changes in biomarkers of cardiovascular disease (CVD) risk." (PMID 37367662, 2023). "In this way, insulin production increases at the same time as hyperglycemia decreases." (PMID 37447270, 2023). "However, it is notable that the early insulin (and C-peptide) response to hyperglycemia — perhaps a surrogate of first-phase insulin response — was impaired by exendin 9-39 infusion in this group." (PMID 37751301, 2023). "However, according to clinical trials of intensive insulin therapy, Stress hyperglycemia is diagnosed at 1 mmol/L." (PMID 37190521, 2023). "Additionally, we explored the ET-1 pathway in GDM pregnancies treated with either diet or insulin management; when diet intervention alone cannot reduce hyperglycemia, insulin treatment is administered." (PMID 37893034, 2023). "Furthermore, it has recently been discovered that β-caryophylleneefficiently protects β-cells in Langerhans islets by relieving hyperglycemia by boosting insulin release." (PMID 37822828, 2023). "Importantly, impairment in lung DC in virally infected Akita mice was rescued by insulin-driven lowering of hyperglycaemia." (PMID 38093014, 2023). "However, patients who depend on insulin are still looking for effective curative therapy to mitigate hyperglycaemia." (PMID 37528147, 2023). "Hyperglycemia induces elevated O-GlcNAcylation of these key transcription factors and cofactors, promoting gluconeogenesis and lipogenesis, which further diminishes insulin sensitivity." (PMID 37189422, 2023). "Patient (P13) suffers from hyperglycemia during clinical trials, even with insulin infusion." (PMID 36983097, 2023). "This could be due to weight gain or rebound hyperglycemia or is possibly attributable to the increased insulin dosage per se." (PMID 37231315, 2023). "Our data indicate an association of decreased insulin sensitivity with increased neuroinflammation after stroke, even in the absence of hyperglycemia." (PMID 36835405, 2023). "Administration of short or long-acting SC insulin was not unusual and associated with more frequent hyperglycaemia." (PMID 37330419, 2023). "However, over time, the dysfunctional beta cells are unable to keep up with this increased insulin demand, resulting in a decline in insulin production, further perpetuating hyperglycemia." (PMID 38192911, 2023). "In addition, renal dysfunction leads to changes in the pharmacokinetics of exogenous insulin and oral antidiabetic agents, resulting in increased frequency of hypo- and hyperglycemia." (PMID 37089609, 2023). "In addition, chronic hyperglycemia-induced oxidative stress can lead to ER stress and defective insulin secretion by disturbing the ubiquitin-proteasome system." (PMID 37244925, 2023).
Hyperglycemia (continued). "However, females in HFHSD+L that resisted acute hypoglycemia the best also remained in reactive hyperglycemia for the longest time, which can be explained by their highest tendency to develop insulin resistance relative to other animal groups." (PMID 37929025, 2023). "Furthermore, regulation of insulin signalling by p110α also contributes to PI3Kα inhibitor-related hyperglycaemia." (PMID 36773078, 2023). "On that note, we cannot exclude that beta cell degranulation due to chronic hyperglycemia might contribute to the rather low insulin-positive area detected in transgenic animals." (PMID 37813862, 2023). "In fact, it has been reported that pro-inflammatory cytokines (e.g., TNFα, interleukin 1β (IL-1β), interleukin 18 (IL-18) and IL-6) are increased in acute hyperglycemia, whereas in the opposite condition, when insulin is working, these cytokines are significantly decreased." (PMID 38137918, 2023). "One potential explanation is that diets with higher DII and DIL may trigger more pronounced postprandial glucose and insulin responses, resulting in prolonged hyperglycemia and dyslipidemia." (PMID 38049837, 2023). "mTOR-I administered to an animal model of nutrition-dependent type 2 diabetes (diabetic Psammomys obesus) worsened the metabolic state of the diabetic animals: augmented insulin resistance, β-cell dysfunction, and death, thereby preventing β-cell adaptation to hyperglycemia." (PMID 37250653, 2023). "Functioning as insulin secretagogues, they are instrumental in managing postprandial hyperglycemia." (PMID 37915365, 2023). "Furthermore, smoking induced hyperglycemia and significant reductions in serum insulin and leptin levels." (PMID 37189762, 2023). "This provides strong support to the idea that some of the phenomena observed in the kidney of T2DM is caused by insulin itself rather than by hyperglycemia." (PMID 37959313, 2023). "Although the glucose level of patients in cluster C usually falls within target range, it has great variability, which could indicate the need for changing their insulin regimes to reduce fluctuation and hyperglycemia events." (PMID 38875568, 2023). "As a consequence, we observed that MSI-1436-treated horses exhibited lower circulating concentrations of insulin and glucose compared to untreated animals, which displayed critical hyperinsulinemia, hyperglycaemia and hypoadiponectinemia as prominent EMS clinical manifestations." (PMID 37020593, 2023). "Furthermore, others have reported that active management of hyperglycaemia with insulin can improve patient outcomes." (PMID 36158799, 2022). "The explanation of BMI-1’s role in insulin signaling and PHLPP regulation may contribute to a better understanding of mechanisms underlying hyperglycemia and cancer progression." (PMID 36497428, 2022). "It has been shown that common carp has much higher insulin levels than terrestrial mammals, even in the fasted state; in glucose tolerance tests, the vast majority of fish showed persistent symptoms of hyperglycemia after glucose infusion." (PMID 36590418, 2022). "This might be related to the preserved endogenous insulin secretion and relatively short exposure to hyperglycemia in patients with prediabetes." (PMID 36128447, 2022). "In addition, a parallel, double-blind RCT55 examined treatment with linagliptin and insulin or insulin alone in 73 inpatients with COVID-19 and hyperglycemia." (PMID 36472874, 2022). "It is less likely that the hyperglycemia is due to pancreatic damage and thus an absence of insulin due to the loss of beta islet cells, as autopsy done after organophosphate poisoning showed intact pancreas despite extreme hyperglycemia." (PMID 36532913, 2022). "In situations of long-term high blood glucose (hyperglycemia), cells may stop responding to insulin, a condition known as insulin resistance." (PMID 37073169, 2022).